CDC42EP3 (CDC42 effector protein 3)
Diseases named in the same sentence as CDC42EP3 in open-access papers (continued):
Sharing a sentence is not in itself a finding about the gene and the disease.
cancer (17 papers, 2013 to 2025). A tumor composed of atypical neoplastic, often pleomorphic cells that invade other tissues. "For example, Cdc42EP3 is overexpressed in cancer-associated fibroblasts (CAFs), where it plays an important role in CAF activation by promoting mechanotransduction via stress fiber and septin filament formation." (PMID 39971161, 2025). "In cancer-associated fibroblasts, the Cdc42EP3/BORG2-dependent dense actomyosin and septin network allows high contractility and increased mechano-responsiveness to changes in extracellular matrix stiffness." (PMID 36875762, 2023). "A previous study has suggested that CDC42EP3 was identified as a regulator of cancer-associated fibroblast (CAF) functions." (PMID 35365622, 2022). "GO and KEGG functional enrichment analysis indicated the co-expression genes of CDC42EP3 mainly involved in several cancer-associated signaling pathways, such as focal adhesion, ECM-receptor interaction and Hippo signaling pathway." (PMID 34616622, 2021). "Till now, the studies concerning the function of CDC42EP3 mainly aimed on its role in cancer-associated fibroblasts (CAFs)." (PMID 33726765, 2021). "Cdc42EP3/BORG2 has been reported to be needed for matrix remodeling, invasion, angiogenesis, and the tumor growth-promoting abilities of cancer-associated fibroblasts." (PMID 34566889, 2021). "CDC42EP3-206 was the most predictive of irAE risk across cancer types (Rs = 0.79, p = 5.8e-05), followed by TMEM138-211 (Rs = 0.77, p = 1.1e-04)." (PMID 34899357, 2021). "Recently, Cdc42EP3/BORG2 was shown to coordinate actin and septin cytoskeleton rearrangements in cancer-associated fibroblasts (CAFs)." (PMID 27248291, 2017). "Similarly, Cdc42ep3 has been shown to regulate the organization of septin filaments in cancer-associated fibroblast cells." (PMID 36923257, 2023). "Some studies showed that CDC42EP3 plays a role in the function of cancer-associated fibroblasts and DNA damage repair, both of which could be adjusted Cdc42." (PMID 33726765, 2021). "A recent study suggested that CDC42EP3 is a key regulator of cancer-associated fibroblasts." (PMID 31532791, 2019). "Cdc42EP3 is also upregulated in multiple cancers, including glioma, osteosarcoma, gastric cancer, and colorectal cancer." (PMID 39971161, 2025). "While septin and actin distributions have not been directly examined in these cells, it is evident that Cdc42EP3 has strong physiological relevance in the context of cancers and cancer-related pathologies." (PMID 39971161, 2025). "In each of these cancers, knocking down Cdc42EP3 reduced cell viability, proliferation, impaired migration, increased apoptosis, and tumors in mice were smaller." (PMID 39971161, 2025). "The main consequence was a drastic functional inactivation of CAFs, as Cdc42EP3-depleted CAFs presented reduced matrix remodeling, cancer cell invasion, angiogenesis and tumor growth promoting abilities, a phenotype that was mimicked by SEPT2-depletion." (PMID 27248291, 2017). "We propose that Cdc42EP3 expression induced by cancer cells or inflammatory signals in the stroma of pre-malignant lesions would sensitize fibroblasts to respond to changes in the physical environment." (PMID 27248291, 2017). "We also observed that Cdc42EP3 upregulation occurred early during fibroblast activation in cancer in response to multiple factors, including HGF, TGFβ, and SDF-1α." (PMID 27248291, 2017). "More importantly, Cdc42EP3 is required for most of the hallmarks of CAFs, notably extracellular matrix remodelling and promotion of angiogenesis, cancer cell growth and invasion." (PMID 27913681, 2016). "In addition, CDC42EP3 also plays an important role in the occurrence and development of human cancers." (PMID 34616622, 2021). "In addition, we established a trivariate model composed of CDC42EP3-206, TMEM138-211, and IRX3-202, that could better predict the risk of irAE across various cancer types, indicating a potential application as promising biomarkers for irAE." (PMID 34899357, 2021).
cancer (continued). "However, in our study, CDC42EP3 gene expression was downregulated in TN-IBC samples, which suggests that CDC42EP3-regulated cancer-associated fibroblasts may not contribute to the aggressiveness of TN-IBC." (PMID 31532791, 2019). "Also, HOPX was correlated with genes in a manner toward suppression of cancer cell progression; downregulation of TNRC6C, PAX8, TSHR, DYRK1A/B, and SLIT3 (pro-proliferation/migration), and upregulation of PCDH8/9, CDC42EP3/4/5, and TJP3 (anti-proliferation/migration)." (PMID 31666923, 2019).
tumor (15 papers, 2014 to 2026). "The expression of CDC42EP3 in tumor and normal brain tissues were examined through immunohistochemistry and we found the likelihood of CDC42EP3 overexpression was positively correlated with pathological grading." (PMID 35365622, 2022). "To examine the potential influence of CDC42EP3 depletion on in vivo tumor growth, we established mouse models through subcutaneously injecting experimental U251 cells and recorded the growth of xenograft tumors in detail." (PMID 35365622, 2022). "The correlation between increased CDC42EP3 and tumor progression has been identified in several tumor types." (PMID 35365622, 2022). "Tumor tissues with advanced grades were also accompanied with upregulated expression of CDC42EP3, demonstrating a potential linkage between the two." (PMID 33726765, 2021). "The current studies concerning the biological roles of CDC42EP3 have been mainly focused on its regulatory effect on tumor progression." (PMID 34616622, 2021). "As the results, we showed that CDC42EP3 was significantly upregulated in CRC, and its high expression was associated with tumor progression." (PMID 33726765, 2021). "We recently demonstrated a key role of Cdc42EP3 in the emergence of CAFs, stromal cells that promote tumour progression and therapeutic resistance." (PMID 27913681, 2016). "Previous experiments showed MicroRNA-141 could hinder tumor growth and metastasis in PCa by regulating CDC42EP3." (PMID 38829766, 2024). "Inhibition on tumor growth mediated by CDC42EP3 depletion was further verified in vivo." (PMID 35365622, 2022). "In vivo results further confirmed knockdown of CDC42EP3 attenuated tumor growth in CRC." (PMID 33726765, 2021). "Among these genes, PADI3 (peptidyl arginase deiminase 3) and CDC42EP3 (CDC42 effector protein 3) are of particular interest because of their roles in macrophages and tumor biology." (PMID 31532791, 2019). "Specifically, CDC42EP3 may perform a function through regulating c-Myc-mediated transcription of CCND1 in both experimental cell lines and tumor-promoting effects were significantly suppressed following knockdown of CCND1 in U251 cells." (PMID 35365622, 2022). "Specifically, the CDC42EP3-206 + TMEM138-211 + IRX3-202-based model achieved maximum predictive efficacy (Rs = 0.94, FDR = 1.8e-09), explaining more than 88% of the ROR variance observed across different tumor types." (PMID 34899357, 2021). "In addition, Cdc42EP3 expression is also up-regulated during a TGF-β-induced EMT in human keratinocytes, and numerous studies are reporting the differential expression of Borgs in tumoural settings." (PMID 27913681, 2016).
infection (4 papers, 2011 to 2025). The state of being infected such as from the introduction of a foreign agent such as serum, vaccine, antigenic substance or organism. "CDC42EP3 mRNA levels were down regulated in host cells upon infection with L. donovani." (PMID 25299267, 2014). "Thus, downregulation of CDC42EP3 transcription after a 72 hr and 96 hr infection may be an additional mechanism that Leishmania uses to direct host phagosomes to form phagolysosomes to ensure amastigote survival." (PMID 25299267, 2014). "Of those tested Cdc42ep3 (CDC42 effector protein), ARHGDIB (Rho GDP dissociation inhibitor (GDI) beta), Acta2 (Alpha actin 2), Egr2 (Early growth response 2), IL-6 (Interleukin 6) and Vav3 (vav 1 guanine nucleotide exchange factor), were induced by EPEC infection but not by infection with EPEC Δtir." (PMID 21490959, 2011).
CDC42EP3 also shares sentences with these, for which no sentence is quoted: asthma (1 paper); cervical adenocarcinoma (1); diabetes (1); E. coli infection (1); gynecological tumors (1); lung carcinoma (1); pancreatic acinar carcinoma (1); periodontitis (1); viral infections (1).